MIR205 (microRNA 205)
Synonyms: hsa-mir-205; MIRN205; mir-205
Gene: MicroRNA gene on chromosome 1 (209,432,133 to 209,432,242, forward strand). Ensembl gene ENSG00000284485.
Gene Ontology:
Biological process: miRNA-mediated post-transcriptional gene silencing
Cellular component: RISC complex
Homologues: Orthologues: chimpanzee ptr-mir-205 (100% identical), macaque mml-mir-205 (98% identical), tropical clawed frog xtr-mir-205a (64% identical), rabbit MIR205 (63% identical), dog MIR205 (62% identical), pig ssc-mir-205 (62% identical), mouse Mir205 (59% identical), zebrafish dre-mir-205 (58% identical), guinea pig MIR205 (55% identical).
Diseases named in the same sentence as MIR205 in open-access papers:
MIR205 is named in the same sentence as 6 diseases in open-access papers, as found by Europe PMC text mining. Sharing a sentence is not in itself a finding about the gene and the disease. The quoted sentences say what the papers report.
melanoma (2 papers, 2017 to 2024). A malignant, usually aggressive tumor composed of atypical, neoplastic melanocytes. "Accordingly, MIR205 is frequently downregulated in melanoma." (PMID 28704519, 2017). "This study aimed to investigate the role of long non-coding RNA MIR205 host gene (lncRNA MIR205HG) in proliferation, invasion, and migration of melanoma cells via jumonji domain containing 2C (JMJD2C) and ALKB homolog 5 (ALKBH5)." (PMID 38252669, 2024).
prostate carcinoma (1 paper, 2022). A carcinoma that arises from epithelial cells of the prostate gland. "MIR205 diminishes the radio-resistance of prostate cancer cells via downregulating TP53INP1, inhibiting autophagy and causing a subsequent impairment in viability and survival." (PMID 35317831, 2022). "It seems that the expression level of miRNAs with anti-tumor activity decreases in hypoxic conditions; in these conditions, MIR30A and MIR205 undergo downregulation to promote prostate cancer progression." (PMID 35317831, 2022). "Further studies reveal an interaction between MIR205 and NKX2-3 that determines the therapy response of prostate cancer patients." (PMID 35317831, 2022). "However, enhancing levels of MIR30A and MIR205 downregulate the level of TP53INP1 via binding to its 3′-UTR to suppress autophagy, resulting in an increased radio-sensitivity of prostate cancer cells." (PMID 35317831, 2022).
cancer (1 paper, 2022). A tumor composed of atypical neoplastic, often pleomorphic cells that invade other tissues. "LncRNA MIR205 host gene (MIR205HG) has been investigated in multiple cancers, however, its role in HB remains to be elucidated." (PMID 34996511, 2022).
tumor (1 paper, 2017). "We thus confirmed MIR205-5p and MIR136-5p expression in tumor tissue: MIR205-5p expression was elevated in tumor compared to normal tissue; and MIR136-5p expression was reduced in tumor compared to normal tissue for most of analyzed samples." (PMID 28704519, 2017).
MIR205 also shares sentences with these, for which no sentence is quoted: osteosarcoma (1 paper); psoriasis (1).